P4HB (prolyl 4-hydroxylase subunit beta)
Diseases named in the same sentence as P4HB in open-access papers (continued):
Sharing a sentence is not in itself a finding about the gene and the disease.
brain tumours (1 paper, 2017). "As such, it is conceivable, though unproven, that high P4HB expression in brain tumours may also exert impact on disease progression and clinical outcome." (PMID 29069756, 2017).
Cachexia (1 paper, 2021). Severe weight loss, wasting of muscle, loss of appetite, and general debility related to a chronic disease. "Collectively, these results suggested that P4HB played a crucial role in inducing muscle wasting, which might be the potential cellular mechanism of regulating cachexia in vivo." (PMID 33732415, 2021). "Importantly, using our ESCC model of cachexia, we successfully identified PHGDH as a target of P4HB in cachexia‐associated muscle wasting." (PMID 33732415, 2021). "Higher P4HB levels were also observed in cachexia‐inducible cells, including AGS, BxPC3 and LLC." (PMID 33732415, 2021). "Additionally, we proved that the P4HB inhibitor, CCF642, not only rescued apoptosis of muscle cells in vitro, but also prevented body weight loss and muscle wasting in ESCC‐induced cachexia mouse model." (PMID 33732415, 2021). "In the present study, we first developed an ESCC‐induced cachexia mouse model using YES2 cell line, and demonstrated that P4HB was a crucial mediator of muscle wasting in vitro and in vivo." (PMID 33732415, 2021). "Overexpression of P4HB in non‐cachexia‐inducible cell line, KYSE150, resulted in the development of significant features of cachexia in nude mice." (PMID 33732415, 2021). "In addition, elevated levels of P4HB in cells and EVs were observed not only in YES2, but also in various types of cachexia‐inducible cancer cell lines originated from both human and mouse, including AGS, BxPC3, and LLC." (PMID 33732415, 2021). "Here, we developed an ESCC‐induced cachexia mouse model using human xenograft ESCC cell lines and found that ESCC‐derived extracellular vesicles (EVs) containing prolyl 4‐hydroxylase subunit beta (P4HB) induced apoptosis of skeletal muscle cells." (PMID 33732415, 2021).
Chlamydia infection (1 paper, 2025). "However, in the Chlamydia group, P4hb showed significantly lower expression, suggesting that Chlamydia infection might suppress P4hb, significantly inhibiting GC cell lineage differentiation and leading to a reduction in the number of intestinal GC cells." (PMID 40786607, 2025).
craniosynostosis (1 paper, 2025). Craniosynostosis is defined as the premature fusion of one or more cranial sutures leading to secondary distortion of skull shape resulting in skull deformities with a variable presentation. "Heterozygous pathogenic P4HB variants are associated with Cole–Carpenter syndrome (CLCRP1), which is an OI-like disorder diagnosed in early childhood with multiple fractures and extraskeletal manifestations, such as craniosynostosis, bone deformities, and ocular proptosis." (PMID 41128774, 2025).
fibrosis (1 paper, 2014). the formation of excess fibrous connective tissue in an organ or tissue in a reparative or reactive process. "In fibrosis, an increase in the expression of collagen-modifying enzymes such as prolyl hydroxylase (e.g. P4H1, P4HB) and lysyl hydroxylase (e.g. PLOD1 and -2) has been shown in e.g. lung and skin fibrosis." (PMID 24622053, 2014).
HIV-1 infection (1 paper, 2025). The type species of lentivirus and the etiologic agent of acquired immunodeficiency syndrome (AIDS). "Most commonly implicated in HIV-1 infection are the enzymes thioredoxin-1 (Trx1, TXN) and protein disulfide isomerase (PDI, PDIA1, P4HB), which share an enzymatic (thioredoxin-family) motif and many targets, initiating disulfide exchanges to modulate protein conformation." (PMID 39912667, 2025).
Kawasaki disease (1 paper, 2023). A rare inflammatory disease characterized by an acute febrile, systemic, self-limiting, medium-vessel vasculitis primarily affecting children. "Increased P4HB expression was also produced in the serum of the Kawasaki disease causing systemic vasculitis." (PMID 36819785, 2023).
keloid (1 paper, 2022). An irregularly shaped, elevated mark on the skin caused by deposits of excessive amounts of collagen during wound healing. "In our research, we detected upregulated BiP and PDI, which help to correct the folding of proteins, including P4HB, PDIA3, and PDIA6 in keloids." (PMID 35435317, 2022).
lung squamous cell cancer (1 paper, 2023). "CAT, ENO1, NQO1, P4HB, and PDIA6 were unique to LUAD, while CAV1, GAPDH, GPX2, GPX3, and PDIA4 exhibited consistent trends in differential expression in both LUAD and lung squamous cell cancer, significant prognostic survival prediction (p<0.05), and excellent classification effectiveness." (PMID 37955007, 2023).
malnutrition (1 paper, 2020). Inadequate nutrition resulting from poor diet, malabsorption, or abnormal nutrient distribution. "The cluster formed CALR, HSPA5, P4HB and, PDIA6 is a potential indicator of maternal malnutrition on the endoplasmic reticulum dysfunction in the prostate of offspring since they act as the fundamental molecular machinery for correct protein folding and Ca2+ homeostasis." (PMID 33049715, 2020).
melanoma (1 paper, 2022). A malignant, usually aggressive tumor composed of atypical, neoplastic melanocytes. "Despite the literature that showed clear evidence for the role of PDI in melanoma, for our bioinformatics analysis, no significant alteration was observed in PDI (P4HB) expression among the different stages of the disease." (PMID 35326089, 2022).
mucinous adenocarcinoma (1 paper, 2020). An invasive adenocarcinoma composed of malignant glandular cells which contain intracytoplasmic mucin. "The samples with overall highest number of expressed P4HB isoforms were smooth muscle cells – aortic samples, followed by CD19+ B cells and mucinous adenocarcinoma cell line." (PMID 33148170, 2020).
osteochondrodysplasia (1 paper, 2023). A term referring to disorders characterized by abnormalities in the development of bones and cartilage. "Although loss‐of‐function mutations in TAPT1, SUCO and P4HB in humans all result in osteochondrodysplasia‐like phenotypes, the homologs of these genes in lower organisms lead to unrelated phenotypes when absent." (PMID 36652330, 2023).
ovarian endometriosis (1 paper, 2010). A non-neoplastic disorder characterized by the growth of endometrial tissue in the ovaries. "Hsp90aa1 expression is up-regulated in ovarian endometriosis while P4hb is involved in post-translational modifications of procollagen synthesis." (PMID 21210965, 2010).
pancreatic adenocarcinoma (1 paper, 2021). "However, cachexia‐inducible pancreatic adenocarcinoma cell line AsPC1 did not express P4HB." (PMID 33732415, 2021).
Papillary Craniopharyngioma (1 paper, 2021). A craniopharyngioma composed of sheets of squamous epithelium which separate to form pseudopapillae. "Additionally, one protein (P4HB) was randomly selected from the up-regulated proteins in papillary craniopharyngioma." (PMID 34707096, 2021).
prostatic adenocarcinoma (1 paper, 2024). "Diagnostic accuracy of P4HB and SOX4 in prediction of prostatic adenocarcinoma." (PMID 39118797, 2024). "Relation between the status of ERG and H score and IRS of both P4HB and SOX4 in the studied participants with prostatic adenocarcinoma." (PMID 39118797, 2024).
protein misfolding diseases (1 paper, 2016). "The proteins encoded by APLP2, PTN, DCN, GPNMB, P4HB, and PDIA3, have been associated with either protein misfolding diseases or TSEs but their specific role in prion protein degradation has not been described." (PMID 26807844, 2016).
renal carcinoma (1 paper, 2023). A carcinoma arising from the epithelium of the renal parenchyma or the renal pelvis. "For example, our previous studies and pan-cancer analysis showed that P4HB was closely related to urinary tumors, especially for renal cancer, but more in-depth mechanism were less, which in turn demonstrated the role of P4HB as a potentially therapeutic target." (PMID 38029391, 2023). "In terms of immune regulatory genes, we found P4HB showed greater correlation with them for patients with GBM, UVM, renal cancer, ACC and PRAD, especially for renal cancer, GBM and UVM." (PMID 38029391, 2023).
cancer (80 papers, 2010 to 2026). A tumor composed of atypical neoplastic, often pleomorphic cells that invade other tissues. "Recent studies have shown that P4HB is upregulated in many cancer cell types, in which high expression is closely associated with advanced tumor stage and poor prognosis." (PMID 34620162, 2021). "Alternatively, P4HB activation might influence ER stress responses, which have been implicated in metabolic reprogramming during cancer progression." (PMID 40534096, 2025). "However, the specific mechanisms underlying the effect of P4HB on tumors are still superficial in many cancers." (PMID 38029391, 2023). "Similarly, the cell surface P4HB was associated with the migration of cancer cells and endothelial cells and also the chemoresistance." (PMID 37945567, 2023). "Moreover, P4HB‐overexpressed EVs treatment resulted in activation of satellite cells, which was associated with cancer cachexia." (PMID 33732415, 2021). "Notably, genes such as TTC3, TMSB4X, MGST1, DNAJC3, and P4HB are closely linked to cancer cell proliferation and migration and may serve as key regulators of CC progression." (PMID 41315466, 2025). "P4HB is overexpressed in various cancers and is involved in collagen metabolism, hypoxic responses, and TME regulation." (PMID 41315466, 2025). "Our results support a TNBC model whereby in older cohorts, myeloid cells and CAFs interact with cancer basal cells via LGALS9/P4HB, PPIA/BSG and PLAU/PLAUR signaling to promote EMT and cell motility." (PMID 41188599, 2025). "In the older TNBC cohort, myeloid cells and CAFs interact with cancer basal cells through LGALS9/P4HB, PPIA/BSG, and PLAU/PLAUR ligand/receptor pairs to promote EMT and cell motility, as confirmed by the age-related increase in EMT ARPs." (PMID 39483921, 2024). "Although expression of P4HB is expected in normal tissues due to its role in homeostasis, overexpression of P4HB has been explained by increased protein demand and synthesis in cancer cells, which is one of the fundamentals of carcinogenesis." (PMID 39118797, 2024). "Recently, P4HB has been demonstrated its oncogenic role of tumorigenesis and development in cancers." (PMID 38029391, 2023). "Considering these facts, this perspective presents a comprehensive summary of the effect of P4HB on human cancers through bioinformatic analysis and current experimental evidence." (PMID 38029391, 2023). "While the expression level of LGALS9 was high mostly in TAMs, and also cancer cells and ductal cells, P4HB was found to be widely expressed by cancer cells, ductal cells and TAMs, respectively in our SC datasets." (PMID 37945567, 2023). "P4HB was found to be overexpressed in various cancer types including bladder cancer, renal clear cell carcinoma, hepatocellular carcinoma, and glioblastoma." (PMID 37945567, 2023). "We proposed that P4HB was a potential target and brought new therapeutic opportunities for cancer patients." (PMID 38029391, 2023). "As an addition, the role of P4HB and LGALS9-P4HB interaction needs to be further investigated in cancer." (PMID 37945567, 2023). "A number of inhibitors of P4HAS and P4HB have been shown to exert anti-tumor effects, suggesting that P4H is an achievable target for cancer therapy." (PMID 35846138, 2022). "P4HB, as an autophagy-related gene, can be detected in various diseases that involve inflammation and apoptosis, including cancer, endocrine diseases, and skin diseases." (PMID 36226178, 2022). "P4HB, a beta subunit of prolyl 4-hydroxylase, helps cancer cells survive from apoptosis induced by endoplasmic reticulum stress." (PMID 35036081, 2022). "cBioPortal and UALCAN analyses indicated that altered P4HB and RGS19 mRNA expression was significantly associated with mutations and clinical characteristics (nodal metastasis and cancer stage)." (PMID 32903592, 2020).
cancer (continued). "In particular, prolyl 4-hydroxylase, β polypeptide (P4HB), also known as PDIA1, is upregulated in numerous types of cancer, and its over-expression is associated with advanced-stage tumours and poor prognosis." (PMID 33023153, 2020). "The data clearly points to roles of P4HB in cancer progression and resistance, while its expression is cell and cancer-dependent." (PMID 33053689, 2020). "Recent studies have shown that P4HB is upregulated in many cancer cell types, and its expression correlates with cancer progression and clinical outcome." (PMID 28052026, 2017). "Among these, TM9SF2, ACTR3, TPT1, TPM3, and P4HB overlapped with the risk genes identified in the TCGA-CESC cohort, all showing HR values greater than 1, further supporting their critical role in HPV-associated cancers." (PMID 41315466, 2025). "In most of them, overexpression of P4HB may promote cancer cell survival, tumor angiogenesis, aggressiveness, immunosuppression, resistance to therapy, and decreased drug sensitivity." (PMID 39118797, 2024). "Furthermore, proteomic and protein functional studies revealed a strong association between high levels of PDIs, a family protein disulfide isomerase to which P4HB belongs, and lymphatic invasion in cancers." (PMID 39118797, 2024). "Their interaction with P4HB may orchestrate proper folding of oncogenic proteins, affecting signaling pathways vital for cancer cell proliferation and survival." (PMID 38029391, 2023). "We hypothesized that one of the anti-cancer targets could be achieved by inhibiting the pro-oncogene P4HB, such as using the P4HB inhibitor bacitracin." (PMID 37480146, 2023). "In this perspective, we used bioinformatic analysis and current experimental evidence to demonstrate that P4HB might serve as a potent target in various cancers." (PMID 38029391, 2023). "Moreover, based on the GSCALite, we predicted the top 10 potential drugs targeting P4HB at pan-cancer level." (PMID 38029391, 2023). "The best described PDI isoforms in cancer cells are PDIA1 (P4HB) and PDIA3 (ERP57)." (PMID 35725466, 2022). "Prolyl 4-hydroxylase (P4H) activity is essential for maintenance of the collagen triple helix and P4HAs (P4HA1, P4HA2, P4HA3) plus P4HB are highly expressed in numerous tumors where they may contribute to cancer progression." (PMID 35846138, 2022). "In addition to P4HB, the mRNA targets regulated by hsa-mir-30a also included many cancer therapeutic targets." (PMID 36138770, 2022). "Furthermore, the role of P4HB in myoblast apoptosis was also investigated in another cachexia‐inducible cancer cell line LLC." (PMID 33732415, 2021). "P4HB‐knockdown LLC‐ EVs also inhibited apoptosis of C2C12 myoblasts induced by cisplatin, suggesting that P4HB might be a critical cachectic factor for pan‐cancer types." (PMID 33732415, 2021). "Protein disulfide‐isomerase (P4HB) has been upregulated in many cancer cell types." (PMID 33934566, 2021). "Finally, only P4HB (Prolyl 4-hydroxylase, beta polypeptide) gene was experimentally validated by RT-PCR between control kidney cells and cancer cells." (PMID 32003756, 2020). "Current evidence indicates that although P4HB have been demonstrated to be higher expressed in almost all of tumor samples than in normal samples and it can significantly influence some phenotypes of cancers, like cell proliferation, invasion, migration and even drug sensitivity." (PMID 38029391, 2023). "Consistent with our pan-cancer analysis, our previous studies found that P4HB expression was higher in tumor samples than in normal samples and P4HB downregulation could significantly inhibit the cell proliferation of six PRAD cell lines, including LNCap, C4-2, C4-2B, PC3, DU145 and 22RV1 cells." (PMID 38029391, 2023). "Hence, the classification effectiveness of ten biomarkers which was assessed overall was based on GPX2 and GPX3 as factors from the enriched pathways and CAV1, ENO1, NQO1, and P4HB as factors from functional classes to determine whether a patient had cancer." (PMID 37955007, 2023).
cancer (continued). "Moreover, based on the GSCALite, we predicted the top 10 potential drugs targeting P4HB at pan-cancer level, which might contribute to target drug development and clinical application in the future." (PMID 38029391, 2023). "Additionally, P4HB has been utilized as an autophagy-related prognostic marker for cancer." (PMID 33925460, 2021). "In addition, P4HB has been reported to protect cancer cells from drug-induced apoptosis; these anti-apoptotic properties of P4HB in cancer cells have been accredited to its function to ameliorate ER stress through interaction with a variety of protein partners." (PMID 28052026, 2017). "P4HB has been shown to influence EMT and cancer cell invasiveness, both of which are processes frequently regulated by PI3K/AKT signalling." (PMID 40534096, 2025). "High expression of P4HB has been observed in BLCA cell lines, knockdown of which can inhibit the invasion and proliferation of cancer cells." (PMID 36147509, 2022). "Given that P4HB and RGS19 are the potential clinical values of ARGs for BUC, we further investigated the clinical significance of P4HB and RGS19 and found that these two genes were closely related to nodal metastasis and cancer stage." (PMID 32903592, 2020). "The transcription levels of P4HB and RGS19 were significantly higher in the tumor tissues than in the non-cancerous bladder tissues in subgroup analyses based on gender, age, cancer stage and nodal metastasis status." (PMID 32903592, 2020). "Given P4HB's role in protein folding and GPX7/GPX8's function in scavenging ROS, their interaction could influence the redox environment crucial for cancer cell survival and proliferation." (PMID 38029391, 2023). "For example, the interaction between P4HB and GPX7/GPX8 might impact cancer cell responses to oxidative stress." (PMID 38029391, 2023). "P4HB was reported to be amplified with a high frequency (9.09%) in our ESCC cases and multiple types of cancer, and its overexpression could predict poor survival of patients with ESCC." (PMID 33732415, 2021). "The P4HB (also known as PDIA1) and PDIA4, which were chosen from the six-gene signature, belong to the protein PDI protein family and have been proved to be related to ER stress activation in human cancers, especially the PERK signaling pathway." (PMID 34307339, 2021). "P4HB may be further exploited as a potential predictive marker for GBM prognosis and an alternative therapeutic approach for GBM and possibility in other cancers." (PMID 29069756, 2017). "More importantly, multivariate Cox proportional hazards regression analysis demonstrated that P4HB, but not RGS19, is an independent and unfavorable BUC biomarker based on clinical characteristics (age, gender, cancer stage, and pathological TNM stage)." (PMID 32903592, 2020). "To clarify whether P4HB and RGS19 were prognostic factors independent of other clinical variables, we performed univariable and multivariable Cox regression analyses with P4HB, RGS19, and clinical features (age, gender, cancer stage, and pathological TNM stage) as covariates." (PMID 32903592, 2020).